LGI2 (leucine rich repeat LGI family member 2)
Description:
Required for the development of soma-targeting inhibitory GABAergic synapses made by parvalbumin-positive basket cells.
Synonyms: KIAA1916; LGIL2; FLJ10675
Tractability: Antibody: UniProt places it where antibodies can reach, with high confidence; its Gene Ontology location is reachable by antibodies, with high confidence; UniProt predicts a signal peptide or a membrane-spanning region. PROTAC: its protein half-life has been measured.
Gene: Protein-coding gene on chromosome 4 (24,998,847 to 25,030,965, reverse strand). Ensembl gene ENSG00000153012.
Subcellular location: Secreted
Subcellular location (Human Protein Atlas): Centrosome; Predicted to be secreted
Pathways (Reactome):
Developmental Biology: LGI-ADAM interactions
Gene Ontology:
Biological process: inhibitory synapse assembly
Cellular component: extracellular region; non-collagenous component of interstitial matrix
Genetic constraint (gnomAD): Loss-of-function variants: 24 observed, 41.81 expected, observed/expected ratio (o/e) 0.57, 90% interval 0.41 to 0.81. The upper end of that interval is the gene's LOEUF score, 0.81, which puts it in group 3 of 6, group 1 being the genes least tolerant of losing a copy. Missense variants: 497 observed, 611.13 expected, observed/expected ratio (o/e) 0.81, 90% interval 0.75 to 0.88. Synonymous variants: 237 observed, 243.6 expected, observed/expected ratio (o/e) 0.97, 90% interval 0.87 to 1.08.
Homologues: Orthologues: chimpanzee LGI2 (100% identical), macaque LGI2 (99% identical), guinea pig LGI2 (98% identical), pig LGI2 (98% identical), mouse Lgi2 (98% identical), rat Lgi2 (98% identical), dog LGI2 (97% identical), tropical clawed frog lgi2 (81% identical), rabbit LGI2 (79% identical), zebrafish lgi2a (69% identical), zebrafish lgi2b (60% identical), Drosophila melanogaster kek3 (19% identical), and 3 more. Paralogues in human: LGI1 (55% identical), LGI3 (51% identical), LGI4 (40% identical), LGR6 (20% identical), LRIG1 (19% identical), LGR5 (18% identical), LRIG2 (18% identical), LRIG3 (18% identical), LGR4 (17% identical), ELFN1 (16% identical), ELFN2 (15% identical), TRIL (15% identical), and 10 more.
Diseases named in the same sentence as LGI2 in open-access papers:
LGI2 is named in the same sentence as 11 diseases in open-access papers, as found by Europe PMC text mining. Sharing a sentence is not in itself a finding about the gene and the disease. The quoted sentences say what the papers report.
epilepsy (11 papers, 2010 to 2024). A brain disorder characterized by episodes of abnormally increased neuronal discharge resulting in transient episodes of sensory or motor neurological dysfunction, or psychic dysfunction. "Lgi2 likely has similar functions as it also interacts with these Adam proteins and mutations in the gene cause epilepsy in dogs." (PMID 28558017, 2017). "Following the line of evidence presented in this paper and collected from previous reports, we arrive at the conclusion that LGI1 and LGI2 apparently share the cellular mechanism of causing genotypically distinct but phenotypically related forms of epilepsy." (PMID 20863412, 2010). "So far, little is known about the function of LGI2, apart from its association with epilepsies." (PMID 31316547, 2019). "LGI2 belongs to the leucine-rich glioma-inactivated (LGI) family, whose mutations have been associated with human epilepsy." (PMID 39144720, 2024). "Lgi2 encodes a secreted LRR protein of the Lgi subfamily that has been implicated in synaptic development and epilepsy." (PMID 28558017, 2017). "Considering that BFJE occurs only during the pruning phase, these results suggest that LGI2's main functions take place in the developmental phase preceding the phase in which the epilepsy occurs." (PMID 21829378, 2011). "LGI2 should be considered a candidate gene for common remitting childhood epilepsies, and LGI2-to-LGI1 transition for mechanisms of childhood epilepsy remission." (PMID 21829378, 2011). "We provide substantial arguments for LGI2 as candidate for epilepsy phenotypes compatible with PEPS." (PMID 20863412, 2010). "Both LGI2 and FGF13 mutations are implicated in syndromes with epilepsy as a component." (PMID 31297048, 2019). "LGI2 and FGF13 dysfunction have also been linked to epilepsy." (PMID 31297048, 2019). "ADAM23 binds two epilepsy-associated proteins, LGI1 and LGI2." (PMID 22457775, 2012). "LGI2 should be considered a candidate gene in these common epilepsies." (PMID 21829378, 2011). "In summary, wt LGI2 binds the same ADAM substrates of LGI1 following secretion, and the Lagotto K518X mutation prevents secretion and ADAM interaction, in the same fashion as the well-characterized truncating LGI1 epilepsy mutations." (PMID 21829378, 2011). "The LGI2 (leucine-rich, glioma inactivated 2) gene, a prime candidate for partial epilepsy with pericentral spikes, belongs to a family encoding secreted, beta-propeller domain proteins with EPTP/EAR epilepsy-associated repeats." (PMID 20863412, 2010). "Importantly, LGI2 expression is highest in the phase preceding pruning and epilepsy." (PMID 21829378, 2011). "Experimental testing of cellular effects of mutations in both LGI1 and LGI2 reported in this work results in an effective doubling of experimentally characterized mutations in LGI proteins and, hence, generally advances our understanding of molecular disease mechanisms of LGI-related epilepsies." (PMID 20863412, 2010). "ADAM23 plays a role in synaptic transmission and interacts with known epilepsy genes, LGI1 and LGI2, and should be considered as a candidate gene for human epilepsies." (PMID 26084559, 2015). "However, in almost all of these adult cases no LGI2 gene mutation was identified, suggesting that there might exist a second and distinct form of epilepsy in the Lagotto Romagnolo." (PMID 26316206, 2015). "Hence, we suggest that there is a similar underlying disease mechanism for LGI1 and LGI2 and we propose that each of the LGI family members might be responsible for phenotypically similar, mechanistically related but genotypically distinct forms of epilepsy." (PMID 20863412, 2010). "ADAM23 interacts with known epilepsy proteins LGI1 and LGI2." (PMID 22457775, 2012). "Hence, this functional LGI2-to-LGI1 transition may explain the benign and remitting course of epilepsy in the Lagotto Romagnolo breed." (PMID 26316206, 2015).
epilepsy (continued). "LGI2 is a paralog of LGI1 which is the causal gene for ADTLE/ADPEAF (autosomal-dominant temporal lobe epilepsy/autosomal dominant partial epilepsy with auditory features, MIM# 600512), a non-remitting epilepsy in humans with onset typically in adolescence or early adulthood." (PMID 26084559, 2015). "LGI2 acts at least in part through the same ADAM receptors as LGI1, but earlier, ensuring electrical stability (absence of epilepsy) during pruning years, preceding this same function performed by LGI1 in later years." (PMID 21829378, 2011).
familial temporal lobe epilepsy-1 (1 paper, 2012). "Mutations in ADAM23 have not been found in epileptic patients, but it interacts with LGI1, a gene associated with familial temporal lobe epilepsy-1 (ETL1) in human and with LGI2, which is the causative gene for benign focal epilepsy in dogs." (PMID 22457775, 2012).
lung carcinoma (1 paper, 2020). "Of these, the functions of GSTA1 and HAS1 in lung cancer have been reported, whereas the role of LGI2 in cancer remained unknown." (PMID 32209727, 2020).
lung squamous cell carcinoma (1 paper, 2024). "Further studies have confirmed the overexpression of LGI2 in patients with lung squamous cell carcinoma and in non-melanoma skin cancer model mice." (PMID 39144720, 2024).
partial epilepsy (1 paper, 2010). "In our previous work, arguments based on protein sequence analysis and patient-specific chromosomal deletions are provided for LGI2 as the prime candidate gene for partial epilepsy with pericentral spikes (PEPS)." (PMID 20863412, 2010).
neurological disorders (1 paper, 2022). "Both LGI2 and SEPSECS are essential genes related to neurological disorders, and they could affect development of the early nervous system." (PMID 35372529, 2022).
LGI2 also shares sentences with these, for which no sentence is quoted: cancer (1 paper); Dystonia (1); non-melanoma skin carcinoma (1); schizophrenia (1); tumor (1).